SOX2 (SRY-box transcription factor 2)
Diseases named in the same sentence as SOX2 in open-access papers (continued):
Sharing a sentence is not in itself a finding about the gene and the disease.
cancer (continued). "SOX2 is required for stem-cell maintenance in the central nervous system, and Sox2-dependent activation of Wnt signaling drives the development of tamoxifen resistance in cancer stem/progenitor cells." (PMID 25605243, 2015). "Close concomitant expression patterns of SOX2OT and SOX2 in stem cells and some human cancers, have all suggested that they may be co-regulated and involved in similar molecular pathways." (PMID 26136768, 2015). "Prior studies suggest OCT4 and SOX2 have a key role of tumorigenesis and prognosis of cancer." (PMID 26706028, 2015). "Thus, SOX2 induction isconsistently observed following acute withdrawal of EGFR signals in cancer models aswell as in patient-derived cells that exhibit oncogene dependence on the EGFRpathway." (PMID 25686219, 2015). "Indeed, this contention is supported by cancer biology studies that have shown a correlation between expression of Oct4 and Sox2 protein and increased resistance of cancer cells to radiotherapy." (PMID 26528440, 2015). "However, the pattern of SOX2 expression and its correlation with clinical/pathological outcomes of various cancers is highly controversial." (PMID 26370982, 2015). "In this review, we have delineated the complex structure and functional features of SOX2OT locus, with more emphasis on its expression and splicing patterns, and its potential role in the regulation of SOX2 expression during the development and cancer progression." (PMID 26136768, 2015). "Overexpression of SOX2 can lead to generation of cancer stem cells (CSCs) within the brain." (PMID 26580604, 2015). "In light of the essential role of DNAme in the regulation of SOX2 expression we hypothesized that targeted de novo methylation in the SOX2 promoter would result in an epigenetic 'off' switch, forcing cancer cells to undertake differentiation programs." (PMID 25684141, 2015). "Finally, AKT inhibitors efficiently suppress the growth of SOX2-expressing putative cancer stem cells, whereas conventional chemotherapeutics select for this population." (PMID 26498353, 2015). "We found the Oct4, Sox2 and Nanog were obviously upregulated in sphere cells compared with adherent cells, suggesting that the UM-UC-3 and T24 spheres had the characteristics of cancer stem cells." (PMID 25656485, 2015). "SOX2 is overexpressed in renal, prostate, colorectal, esophageal, and lung cancers." (PMID 26023799, 2015). "A role for SOX2 in cancer progression has been reported by several studies." (PMID 28983346, 2015). "SOX2/livin pathway regulates cancer stem cell survival so it could be targeting as an effective therapeutic strategy for cancer treatment." (PMID 28983346, 2015). "Furthermore, the combined treatment also reduced the expression of the stem cell markers Oct 3/4, Nanog, Sox-2 and Snail in cancer cells, and contributed to the diminution of the CSC subpopulation, as indicated by colonosphere formation assays." (PMID 26107817, 2015). "OCT4 and SOX2 are important transcriptional factors involved in maintenance of pluripotency and self-renewal in cancer stem cells, aberrant expression of OCT4 and SOX2 might contribute to carcinogenesis in various cancers." (PMID 26706028, 2015). "The expression of Oct4, Nanog, Myc, Sox2, and Klf4 in the current study correlated well with data reported in the HPA which reveals expression of Oct4 in 88 % of cancers, Sox2 in 88 % of cancers, Myc in 78 % of cancers, Klf4 in 28 % of cancers, and Nanog in 7 % of cancers." (PMID 26412983, 2015). "Expression of OCT4 and SOX2 was evaluated by IHC in cervical neoplasia and cancer specimens." (PMID 26706028, 2015). "Recently, an increasing amount of data indicates SOX2 expression in various cancers." (PMID 26498353, 2015). "Conversely, suppression of Sox2 can impair the chemosensitivity and stemness of cancer cells." (PMID 26499463, 2015).
cancer (continued). "In this connection, HIF-2α may act through up-regulation of KLF4, Sox2 and Octamer-4, to favor de-differentiation and confirmation of stem-cell properties of putative cancer stem cells." (PMID 25544768, 2015). "Recent evidence suggests that EMT could attribute to the generation of CSCs, possibly further implicating SOX2 in a network of tumorigenesis and progression though its expression in a cancer cell subpopulation." (PMID 25156079, 2014). "In many of these studies, Sox2 was found in the cancer stem cell population, supporting the hypothesis that cancer stemness is related to the aberrant expression of ESC proteins." (PMID 25380620, 2014). "According to the results of our study the expression of SOX2 could be the target of choice to eliminate cancer cells with stem-cell-like properties." (PMID 25477962, 2014). "Thus, the response of BC cells to the Sox2 transcription activity reporter has distinguished primary patient and cultured cell lines cancer-cell subpopulations with distinct phenotypic and molecular features." (PMID 25380620, 2014). "This hypothesis is supported by numerous reports showing that SOX2 drives EMT in several cancer models, by upregulating several keystone proteins of this process, namely Snail, Slug and Twist." (PMID 25300947, 2014). "Particularly, the role of SOX2 in cancer pathogenesis has become of interest in the field." (PMID 25114775, 2014). "Using such a system, it may be possible to isolate Sox2-positive cells from low-expressing cancer cell lines, such as HeLa and CaSki cells, or from primary cancer cells obtained from fresh cancer tissues." (PMID 24489842, 2014). "SOX2 has proven its functional role in various aspects of cancer biology." (PMID 25114775, 2014). "Our results therefore provide an important clue as to how SOX2 expression might be controlled in cancer tissue." (PMID 25006803, 2014). "Several studies support the hypothesis that SOX2 is a relevant oncogenic factor in various cancers and recently, SOX2 has been suggested as a putative therapeutic target for early stage EC." (PMID 24404135, 2014). "For these reasons, SOX2 has been heavily investigated in CSCs in several cancer types." (PMID 25114775, 2014). "For this study, 2102Ep and NTera-2 cells could provide significant insights into the post-transcriptional regulatory functions of SOX2 towards both cancer stemness and embryonic stemness." (PMID 25156079, 2014). "Future research could further and individually validate the presented miRNAs and targets in relation to SOX2-linked EMT, embryonic development and cancer." (PMID 25156079, 2014). "Cellular proliferation is tightly regulated by SOX2 in many cancer types." (PMID 25114775, 2014). "Based on the concept generated from this current study, treatments that result in YB-1 inhibition in cancer cells may up-regulate Sox2 expression and transcription activity in the RR cell subset." (PMID 24885403, 2014). "Studies using various experimental models have demonstrated that Sox2 promotes key tumorigenic properties in cancer cells, including proliferation, invasion, migration, colony formation, non-adherent stem cell-associated sphere formations in vitro and tumorigenicity in vivo." (PMID 24885403, 2014). "Interestingly, we found that DDX3X induced increase of cancer cells accompanied by stem-like phenotypes such as upregulated expression of Sox2, ALDH, and CD44." (PMID 25343452, 2014). "This study suggested that the nuclear marker Sox2 may serve as a feasible alternative to surface markers for the isolation of CSCs from somatic carcinomas." (PMID 24489842, 2014). "However, the specific marker antigens Nanog and Sox2 were simultaneously expressed in normal cancer stem cells." (PMID 23604326, 2013). "Three distinct cancer stem cell markers, Nanog, Oct-4 and SOX-2 were assessed." (PMID 23349823, 2013).
cancer (continued). "Indeed, such stem cell reprogramming factors are established oncogenes (c-Myc and Klf4) or are emerging as oncogenes (Sox2, Oct4, and Nanog) in a variety of cancers." (PMID 23326489, 2013). "Furthermore, the expression of SOX2, but not OCT4 or NANOG, induced mammosphere formation in cultures, underscoring the possibility that increased expression of SOX2 is sufficient to induce cancer stem cell properties." (PMID 24355041, 2013). "Cancer cells with high levels of SOX2 expression might also have an impact on the lymph vessel invasion process at the primary site." (PMID 24376714, 2013). "The reprogramming factors OCT4, SOX2, NANOG, KLF4, c-MYC, and LIN28 have also been suggested to be oncogenes and may be implicated in the development of several cancers." (PMID 24040120, 2013). "Transcription factor Sox2 remains the pluripotency of stem cell, participates in self-renew of cancer stem cell and plays important role during the initiation and development of various cancers." (PMID 24229625, 2013). "Moreover, several studies and our data have identified that SOX2 expression correlated with tumorigenesis, chemoresistance, and maintaining the stem cell-like phenotype in cancer cells." (PMID 23990933, 2013). "Among the intralymphatic tissues, low ALDH1 expression in cancer cells, high SOX2 expression in cancer cells, and a high number of CD204(+) macrophages were independent predictive factors for lymph node metastasis (P = 0.004, P = 0.008, and P = 0.028, respectively)." (PMID 24376714, 2013). "Sox2, or Oct4 also plays a pivotal role in cancer development." (PMID 23874550, 2013). "Moreover, the expressions of cancer stem cells markers, such as Oct4, Sox2 and Nanog were gradually decreased when the sphere cells were digested into single cells for re-adherent culture." (PMID 23383988, 2013). "Additionally, we found that cancer stem-like cell markers, such as Sox2, Oct4 and Nanog, were down-regulated when UbB was knocked down, suggesting a crosstalk between UbB signaling and the expression of cancer stem-like cell markers." (PMID 24367661, 2013). "SOX2 is a transcription factor essential for maintaining self-renewal of undifferentiated normal embryonic stem cells, and also plays an important role in cancer development and recurrence." (PMID 24355041, 2013). "Oct4 and Sox2 are overexpressed in some cancer stem cell types." (PMID 24376802, 2013). "Alternatively, we speculate that CSCs/CICs of ES might have more differentiated characteristics with downregulation of Sox2 than those of carcinomas." (PMID 24376795, 2013). "The reason might be that Sox2 and Oct4 mainly express in cancer cells, but a small amount of other cells such as leukomonocytes or interstitial cells can also express these and hence be detected with these tests." (PMID 22837720, 2012). "Identifying genes required by SOX2 for growth promotion may offer new therapeutic targets for the treatment of SOX2-dependent cancers." (PMID 22937156, 2012). "Hypoxia, via HIF-1α-mediated transcription, has been shown to induce an embryonic stem cell-like transcriptional program including pluri-potency-inducing markers like OCT3/4, Nanog, c-Myc, KLF4 and SOX-2 in several cancer cell lines derived from various tissues." (PMID 23185562, 2012). "It was also established that induced pluripotent stem (iPS) or pluripotent cancer (iPC) cells could be generated by co-transfection of Sox2 cDNA with other transcription factors such as Oct4, Klf4 and c-Myc into fibroblast or cancer cells." (PMID 22615765, 2012). "Furthermore, the EMT process is often activated during cancer invasion and metastasis and SOX2 is also over expressed in many types of cancers." (PMID 22912670, 2012). "Moreover, TSA treatment led to further increase in the expression of Sox2 and Nanog in PCa cells with EMT phenotype, which was associated with cancer stem-like cell (CSLC) characteristics consistent with increased cell motility." (PMID 23024790, 2012).
cancer (continued). "Although NSC and ESC are adversely affected by increases in the levels of SOX2, other studies have reported that breast, prostate and lung cancer cells engineered to constitutively express elevated levels of SOX2 (∼3- to 4-fold) exhibit enhanced growth and tumorigenicity." (PMID 22937156, 2012). "By using the RNA-Seq method, an additional 246 target cancer genes of SOX2 were revealed." (PMID 22615765, 2012). "Expression of Sox2 and Oct4 were assayed in cancer tissues and their corresponding paracancerous tissues from 44 patients with NSCLC and 21 patients with benign tumors using immunohistochemistry, Western blot, reverse transcription polymerase chain reaction (RT-PCR)." (PMID 22837720, 2012). "Sox2 is also regarded as a key factor for some cancer progress." (PMID 22837720, 2012). "Importantly, we demonstrate that this is also likely to be true for other cancers that express SOX2." (PMID 22937156, 2012). "Furthermore, SOX2 also maintains self-renewal of cancer stem cells or is activated in cancer stem cells." (PMID 22912670, 2012). "Furthermore, the expression of representative cancer stem cell genes and related proteins, including SOX2, Oct4, and NANOG, was upregulated in spheres compared with those detected in parental cells, at both the RNA and protein levels." (PMID 22359637, 2012). "In particular, a potential development of an amoeboid phenotype after SOX2-RNAi might be dangerous when SOX2 or downstream molecules are targeted in cancer therapies." (PMID 22070920, 2011). "Also, SOX2 was involved in later events of carcinogenesis such as invasion and metastasis of pancreatic and prostate cancers." (PMID 21468047, 2011). "However, the exact biological role of cancer-related SOX2-specific antibody and/or T cell responses has remained unclear." (PMID 22190969, 2011). "In our study, SOX2 was lower in cancers compared with normal tissues." (PMID 21982273, 2011). "In addition, the expression of Oct4 or Sox2 has been reported in the cancer stem-like cells and is related to a cancer patient's prognosis." (PMID 20937145, 2010). "An important feature of our model is that overexpression of Sox2 leads not only to distal hyperplasia and cancer but also to development of a pseudostratified epithelium with p63-positive cells adjacent to the basal lamina and FoxJ1 cilliated cells reaching to the apical surface." (PMID 20548776, 2010). "In order to assess whether a higher level of Sox2 would lead to cancer, we made the mice homozygous for the Rosa26R-Sox2-IRES-GFP allele." (PMID 20548776, 2010). "Over 12–34 weeks, about half of the mice expressing the highest levels of Sox2 develop carcinoma." (PMID 20548776, 2010). "Screening of several key proteins controlling cell cycle, development, metabolism, apoptosis and growth, including Erk, Akt, GSK3β, p16 and p14, Bcl-2, c-Myc, Nestin and Sox2, showed that downregulation of Bmi1 reduced GSK3β protein levels and induced differentiation in cancer cells." (PMID 19823589, 2009). "Importantly, we demonstrated that patients with cancers showing SOX2 methylation had a significantly shorter survival time than those without its methylation." (PMID 18268498, 2008). "To further investigate the role of ES cell factors in diseases, we performed another multiple gene search on Nanog, Oct4 and Sox2 and found that they were all significantly upregulated in abnormal sperm morphology, and significantly downregulated in malaria infection and cancer in human studies." (PMID 19094235, 2008). "In addition, cancer cells cultured as spheroids on non-adherent culture dishes have many stem cell markers (eg, Oct 4, Nanog, SOX2) that are highly upregulated when compared with normal adherent cancer cell cultures." (PMID 18231105, 2008).
cancer (continued). "Sex determining region-Y-related high mobility group box 2 (SOX2), a key transcription factor involved in the maintenance of cellular stemness, has been identified as a potential biomarker in multiple cancer types; however, its prognostic significance in UTUC remains unclear." (PMID 42137465, 2026). "Therefore, identifying and characterizing the molecular mechanisms leading to aberrant SOX2 overexpression in cancers could provide a basis for developing novel therapeutic approaches for various cancers driven by this abnormal overexpression." (PMID 39994220, 2025). "Similarly, overexpression of circFOXK2‐WT could increase MTCO1 expression, complex IV activity, OCR, mtROS, cancer stemness, cisplatin resistance, and SOX2 expression levels in T24‐CIS cells, but circFOXK2‐MUT could not." (PMID 39656941, 2025). "Additionally, sex-determining region Y-box transcription factor 2 (SOX2) and NANOG, which are markers of cancer stem cells, have been implicated in ESCC progression, but their regulation through PP1γ and YAP1 remains unclear." (PMID 40626009, 2025). "Indeed, Lin28 is known to regulate the expression of Sox2, Oct4, and Nanog in various cancer cells." (PMID 39800739, 2025). "In cancer stem cells (CSCs), STAT3 gain-of-function mutations or persistent activation further amplify these effects by promoting the expression of stemness-related transcription factors such as NANOG, SOX2, and OCT4, which are critical for maintaining the CSC phenotype." (PMID 40140827, 2025). "Human cancer stem cells (CSCs) are a known targets of EGCG for cancer prevention and treatment; the fact that EGCG prevents the transcription and translation of genes encoding for stemness markers such as CD44, CD133, Nanog, Oct4, and Sox2 suggests that it averts CSCs from self‐renewing in general." (PMID 40255557, 2025). "Additionally, betavulgarin decreases the levels of proteins like c-myelocytomatosis (C-Myc), Nanog, and octamer-binding transcription factor 4 (Oct4), essential for self-renewal, and inhibits the Stat3/Sox2 signaling pathway, which is vital for cancer stem cell survival." (PMID 39682981, 2024). "Consistent with the genomic results, we found that GluOC promoted the protein expression of OCT4, NANOG, and SOX2, while Y-27632 attenuated this effect, but the addition of GluOC significantly alleviated the effect of the inhibitor and induced the proliferation of cancer cells." (PMID 39054484, 2024). "Interestingly, Sox2 and Klf4 have been pointed out as the relevant reprogramming factors inducing leukemic apoptosis, exemplifying the context dependent effect of the Yamanaka factors in cancer cells of different origin." (PMID 39587064, 2024). "In addition, variable functions of SOX2, regulated by factors such as post-translational modifications (PTMs) could lead to diverse patterns in various cancer types." (PMID 38334608, 2024). "The SOX2 overexpression is commonin many human cancers and is involved in various aspects of metastasisand unfavorably impacts drug resistance, leading to poor survivalrates in cancer patients, whether these principlesextend to bone cells necessitates further investigation." (PMID 38739686, 2024). "However, further studies of SOX2 in a pan-cancer context are warranted." (PMID 38164286, 2024). "In this study, the synergistic effects of Sox2-Oct4 decoy oligodeoxynucleotides-encapsulated Niosomes-zinc hybrid nanocarriers along with X‐irradiation conditions as a combinational therapy tool were investigated in the treatment of cancer-like stem cells (NTERA-2)." (PMID 39071677, 2024). "However, SOX2 is overexpressed in most cancers and is highly detrimental." (PMID 39334449, 2024). "Thus, targeting the oxidation of SOX2 could be a potential therapeutic strategy for cancer treatment." (PMID 38994937, 2024). "Also, Sox2 is important in maintaining the self-renewal and stemness of cancer cells." (PMID 38419894, 2024).